MMP7 (matrix metallopeptidase 7)
Diseases named in the same sentence as MMP7 in open-access papers (continued):
Sharing a sentence is not in itself a finding about the gene and the disease.
breast carcinoma (continued). "Rebeca Santaolalla in a study on the breast cancer cells also showed that TLR-4 enhances migration of breast cancer cells, via PI3K/AKT/GSK3β, and promotes transcription of downstream-catenin target genes (MMP7, MMP9, and VEGFA), leading to breast cancer metastasis." (PMID 34904014, 2021). "Analyses of rs11568818 in MMP-7 performed in Chinese population suggested that rs11568818 may correlate with 2-fold increased risk of lung cancer (243 cases and 350 controls, OR = 2.0, 95% CI = 1.23–3.24 for AG and GG genotypes), but not breast cancer (1079 cases and 082 controls)." (PMID 32765800, 2020). "Similarly, in breast cancer, FAT4 silencing resulted in the upregulation of N-cadherin, MMP-7, and Cyr61 expression and the downregulation of E cadherin, indicating the role of FAT4 in the EMT process." (PMID 32366234, 2020). "Similarly, PERK also contributes to ECM reorganization in breast cancer and overexpression of ATF4, which is a component of PERK pathway, induces cell invasion and metastasis, stimulating MMP2 and MMP7 expression in ESCC." (PMID 33014334, 2020). "Furthermore, shERβMDA-MB-231 breast cancer cells treated with lumican exhibited reduced proteolytic activity of MMP-14 and expression levels of MMP-7." (PMID 28332606, 2017). "We found that ectopic expression of ALX4 could inhibit the canonical Wnt signaling activity in breast cancer by TOP/FOP flash reporter assay and the Wnt target functional genes MMP7, c-Myc and Cyclin D1 were down regulated both at protein and mRNA level." (PMID 29183346, 2017). "Finally, mangiferin has been shown to lower cell viability, suppress metastatic potential, decrease MMP-7 and -9 expression, reverse epithelial-mesenchymal transition (EMT), and inhibit the β-catenin pathway in breast cancer cell lines." (PMID 28464819, 2017). "Other studies have suggested that MMP-7 could be a direct target for STAT3 in gastric and breast cancer cells, which is consistent with our conclusion in pancreatic cancer cells." (PMID 21991388, 2011). "This could be due to a regulation on the translational level, resulting in low levels of MMP-7 mRNA in breast cancer tissue and – as effect of a higher transcriptional rate in breast cancer tissue – higher protein levels of MMP-7 in breast cancer tissue." (PMID 19531263, 2009). "In contrast to MMP24, higher levels of MMP7 expression were associated with lower survival rates in patients with lung cancer, pancreatic cancer, or renal cancer but not colorectal cancer, whereas MMP7 was not a prognostic factor for breast cancer in the Human Protein Atlas database." (PMID 32093160, 2020). "Furthermore, we found that silencing of KIF3B decreased the expression of Dvl2, phospho-GSK-3β, total and nucleus β-catenin, then subsequent down-regulation of Wnt/β-catenin signaling target genes such as CyclinD1, C-myc, MMP-2, MMP-7 and MMP-9 in breast cancer cells." (PMID 33542902, 2020). "However, the relationship between MMP7 and DKK1 remain elusive in breast cancer." (PMID 31285694, 2019). "Reduced SIRT1 levels in HMLER breast cancer cells led to increased metastases in nude mice, and SIRT1 reduces the EMT in cancer and fibrosis by deacetylating Smad4 and repressing the effect of transforming growth factor-β signalling on matrix metalloproteinase-7 (MMP-7), a Smad4 target gene." (PMID 27793039, 2016). "However, the potential role of MMP-7 in human breast cancer, and particularly in clinical breast cancer, has not been thoroughly investigated." (PMID 17342087, 2007). "Notably, the genes LDHB, MMP7, KRT5, KRT14 and KRT15, which were significantly upregulated in the PIPET_Basal subpopulation, are recognized as specific biomarkers of the basal-like molecular subtype or genes typically highly expressed in basal-like breast cancer." (PMID 38819254, 2024).
breast carcinoma (continued). "However, another report identified that Wnt5a could induce invasiveness of cancer cells and the production of matrix metalloproteinase-7 (MMP7) and tumor necrosis factor-α (TNF-α) in macrophages, which was essential for macrophage-induced invasiveness in breast cancer." (PMID 27895670, 2016). "Western blot analysis confirmed this absence of MMP-7 and, furthermore, the basal level MMP-9 and uPA produced by the monocyte cells was not changed upon exposure to the breast cancer CM (results not shown)." (PMID 16168111, 2005). "qRT-PCR analysis of mammary tumors demonstrated increased β-catenin transcriptional activity as judged by enhanced mRNA expression of β-catenin target genes (Cyclin D1, c-Myc, TCF-7, VEGF and MMP7) in the absence of VDR." (PMID 26008979, 2015).
colorectal cancer (92 papers, 2001 to 2026). A primary or metastatic malignant neoplasm that affects the colon or rectum. "In colorectal-cancer patients who received adjuvant 5-FU chemotherapy, high MMP-7 tissue expression was found to be associated with shorter disease-free survival." (PMID 33396213, 2020). "The matrix metalloproteinase-7 (MMP-7) gene -181A>G polymorphism has beenreported to be associated with colorectal cancer (CRC) and gastric cancer(GC) susceptibility, yet the results of these previous results have beeninconsistent or controversial." (PMID 31644669, 2019). "The levels of MMP-7 in sera or saliva have been found to be used as a diagnostic and prognostic marker of patients with colorectal cancer and oral squamous cell carcinoma." (PMID 26699938, 2015). "MMP-7 is secreted specifically by epithelial cells and its over-expression has been observed in many tumor types such as colorectal cancer, epidermolysisbullosa associated skin cancer, bladder cancer, gastric cancers, pancreatic cancer and esophageal cancer." (PMID 25875355, 2015). "Loss of MMP7 either by antisense RNA mediated knockdown in colorectal cancer cell lines or by knockout in mice leads to decreased tumor incidence, while an increase in MMP7 expression causes increased tumor formation." (PMID 25875355, 2015). "We investigated the role of MMP1, MMP3 and MMP7 promoter polymorphisms as colorectal cancer risk factors in a case-control study of cases with large adenomatous polyps (n = 295), versus small adenomatous polyps cases (n = 302) or PF controls (n = 568)." (PMID 17125518, 2006). "Moreover, physodic acid reduced the expression of BIRC5 which encodes survivin in both colorectal cancer cell lines and also tended to decrease the level of MMP7 transcript in HCT116 cells." (PMID 28887754, 2018). "Because EGFR is known to enhance MMP-7 expression in colorectal cancer, we verified whether EGFR was associated with MMP-7, YAP and MRLC on stiffer substrates." (PMID 26344692, 2015). "While most significant correlations were observed in lung cancer cell lines, potentially due to the larger sample size, unexpected correlations were found, such as potential resistance to elesclomol in colorectal cancer cell lines with higher MMP7 expression." (PMID 39393173, 2024). "For example, the identification of colorectal cancer cells with higher MMP7 scores showing resistance to cuproptosis inducer elesclomol highlights the potential for targeted therapies." (PMID 39393173, 2024). "High concentrations of MMP-7 are responsible for excessive proliferation of cancer cells and, consequently, contribute to the metastasis of cancer cells (mainly in the case of colorectal cancer)." (PMID 38203373, 2023). "Studies have shown that the level of MMP-7 was higher in patients with colorectal cancer compared to the level of MMP-7 in patients from the control group, i.e., healthy patients." (PMID 38203373, 2023). "In patients with colorectal cancer, MMP-7 is responsible for cell proliferation by releasing ectodomains, i.e., growth factors." (PMID 38203373, 2023). "Overexpression of Rab11-FIP2 promotes metastasis of colorectal cancer cells through the PI3K/Akt/ Matrix Metalloproteinase 7 (MMP7) pathway, thus affecting the prognoses of these patients." (PMID 36984512, 2023). "Our data provide new insights into the role of F. nucleatum in colorectal cancer metastasis and assist translational research in using F. nucleatum and MMP7 as potential therapeutic targets for the treatment of CRC." (PMID 37814323, 2023).
colorectal cancer (continued). "Matrix metalloproteinase-7 (MMP-7) expression was significantly upregulated in human colorectal cancer cells cultured on rigid polyacrylamide hydrogels, and cell proliferation was more active, which is a sign of poor prognosis in colorectal cancer." (PMID 37260829, 2023). "Further study showed that REG4 expression was associated with lymph node metastasis, distant metastasis, metastatic recurrence in the liver, advanced TNM stage, histologic grade, and MMP-7 expression in colorectal cancer." (PMID 36172286, 2022). "The concentration of MMP-7 was significantly elevated in patients with colorectal cancer compared to healthy controls." (PMID 33916127, 2021). "A recent study investigating the relationship between RAB11FIP2 expression and colorectal cancer progression demonstrated that the AKT1/PI3K pathway was involved in the RAB11FIP2-mediated expression of the oncogenic Matrix metalloproteinase 7 (MMP7)." (PMID 33614606, 2020). "The already reported positive correlation between EGFR and Matrix-metalloprotease-7 (MMP-7) seems to play a role in colorectal cancer, and EGFR-mediated MMP-7 up-regulation promotes epithelial-mesenchymal transition during ovarian endometriosis progression." (PMID 32604857, 2020). "And previous studies had evidenced for involvement of MMP-7 activation in colorectal cancer liver metastases." (PMID 32851100, 2020). "Overexpression of MMP7 is commonly found in colorectal cancers, and this protein can induce increased cellular proliferation (29, –, 32)." (PMID 30696739, 2019). "Recent studies have shown that MMP7 is overexpressed in colorectal cancer tissue in comparison to normal mucosa." (PMID 27431388, 2016). "The prognostic impact of MMP7 serum level in advanced colorectal cancer has already been evaluated before." (PMID 27431388, 2016). "In consistence with our results, increased serum levels of MMP7 and correlation to worse overall survival in colorectal cancer has been reported." (PMID 27431388, 2016). "Upregulation of several MMPs including MMP7, MMP10 and MMP12 in cancerous tissue and adverse association with survival has been evaluated likewise in colorectal cancer." (PMID 27431388, 2016). "Stiff substrates enhanced colorectal cancer cell viability by upregulating MMP-7 expression through a positive feedback loop containing YAP, EGFR, integrin-α2β1 and MRLC, independent of Hippo pathway." (PMID 27765911, 2016). "The findings from this study revealed an inherent role of 5-HT1DR which binds Axin1 and dissociates β-catenin from the complex, moving β-catenin into the nucleus to activate the β-catenin/LEF1/TCF4/MMP-7 pathway in colorectal cancer metastasis." (PMID 26214021, 2015). "Together, these observations suggested that YAP is an important upstream regulatory protein of the levels of MMP-7 expression on stiffer substrates in colorectal cancer." (PMID 26344692, 2015). "We demonstrated a novel regulatory molecular mechanism of the MMP-7 expression by YAP in colorectal cancer." (PMID 26344692, 2015). "Together, these results suggested that MRLC interacted with YAP and that these proteins enhanced the expression of MMP-7 on stiffer substrates in colorectal cancer." (PMID 26344692, 2015). "In many malignancies, including colorectal cancers, MMP7 and MMP9 are overexpressed and play a role in cancer progression by enhancing metastatic potential and tumor invasion." (PMID 23724058, 2013). "In this study, we demonstrate a significant overexpression of IGF-1R, IGF-2 and MMP-7 mRNA in colorectal cancer tissues." (PMID 22159423, 2012). "In particular, MMP-7 has been shown to be overexpressed in 75% of human colorectal cancers and correlate with stages of disease and/or prognosis." (PMID 21423639, 2011).
colorectal cancer (continued). "MMP-7 is also produced by several malignant tumor cells including prostate, gastric, head and neck, lung, hepatocellular, and colorectal carcinomas." (PMID 21629786, 2011). "We have observed in patients with advanced colorectal cancer that MMP7 is an independent prognostic factor for shorter survival, probably because this enzyme can affect tumor cell responsiveness to chemotherapy." (PMID 19266094, 2009). "A previous study reported that the serum MMP-7 level was significantly elevated in patients with ovarian cancer and advanced colorectal cancer." (PMID 19405942, 2009). "Matrilysin (MMP-7) has been shown to correlate with nodal or distant metastasis in colorectal carcinomas; however, its implication in early invasive colorectal carcinomas has not been determined." (PMID 11355941, 2001). "Moreover, the increased expression of MMP7 can enhance the metastatic properties of colorectal cancer cells via activating the MAPK pathway." (PMID 39187937, 2024). "MMP-7 -181A>G polymorphism is associated with increased risk of gastric cancer but not generally with colorectal cancer, except in Asian populations where it significantly increases CRC risk." (PMID 39355481, 2024). "Several pro-angiogenic (VEGF, Ang-2, PIGF, sVCAM-1, MCP-1, MMP-3, CHI3L1, IL-8 and CXCL16) and ECM-degrading (MMP-2 and MMP-7) proteins are known to be elevated after colorectal cancer resection, but in relation to postoperative complications such research remain scarce." (PMID 39167197, 2024). "Thus, we sought to further validate the specific correlation between MMP7 and elesclomol in colorectal cancer." (PMID 39393173, 2024). "In colorectal cancer, nuclear beta‐catenin can regulate MMP‐7 expression." (PMID 32985799, 2021). "Beta‐catenin can regulate the expression of the MMP‐7 in human colorectal cancer." (PMID 32985799, 2021). "However, the association between MMP-7 tissue expression and prognosis in colorectal cancer was evaluated, and it was shown that MMP-7 expression has the potential to be a prognostic marker for a poor 5-year outcome in colorectal cancer." (PMID 34502094, 2021). "In colorectal cancer cells, miR-143 inhibits cell proliferation by decreasing MMP7 expression." (PMID 31756170, 2019). "As for MMP7 for MMP10 overexpression in colorectal cancer specimen is described." (PMID 27431388, 2016). "In addition to this, correlation of elevated serum MMP7 with advanced Dukes ́ stage and prediction of recurrence in colorectal cancer patients was assessed reflecting higher MMP7 release through tumoral cells due to a higher tumor load." (PMID 27431388, 2016). "Furthermore, high expression of MMP7 in colorectal cancer samples exhibits tumor promoting roles in terms of correlation with higher Dukes ́stage, lymph node positivity, poor differentiation and metastases." (PMID 27431388, 2016). "Therefore, we report for the first time the novel mechanism of the modulation of MMP-7 expression by MRLC phosphorylation in colorectal cancer." (PMID 26344692, 2015). "Next, we assessed whether MMP-7 affected the viability of colorectal cancer cells on stiffer substrates." (PMID 26344692, 2015). "We describe a novel molecular mechanism through which stiffer substrates increase MMP-7 expression through interactions with several proteins that might be new therapeutic targets for colorectal cancer." (PMID 26344692, 2015). "Like MMP7, Tenascin-C, another Wnt target gene, is also upregulated in the normal mucosa of Bcat mice, and this persists in the tumors of these mice and in human colorectal cancer samples (n=31)." (PMID 26398937, 2015). "Thus, these proteins generated a positive feedback loop that upregulated the levels of MMP-7, resulting in the promotion of cancer cell proliferation and accelerated the viability of colorectal cancer cells on stiffer substrates." (PMID 26344692, 2015).